PTTG1 (PTTG1 regulator of sister chromatid separation, securin)
Diseases named in the same sentence as PTTG1 in open-access papers (continued):
Sharing a sentence is not in itself a finding about the gene and the disease.
colorectal cancer (19 papers, 2007 to 2025). A primary or metastatic malignant neoplasm that affects the colon or rectum. "In terms of colorectal cancer, PTTG1 overexpression is associated with tumourigenesis, progression and cancer metastasis." (PMID 26264222, 2015). "Overexpression of PTTG1 is an independent prognostic factor for colorectal cancer patients, and knockout of PTTG1 can inhibit the growth and metastasis of colorectal cancer." (PMID 33123466, 2020). "FoxM1 binds to PTTG1 promoter to promote PTTG1 transcription and FoxM1-PTTG1 pathway promotes colorectal cancer metastasis." (PMID 30744076, 2019). "Anti-cancer agents such as oxaliplatin modulate the cytotoxicity induction of cancer cells via regulation of PTTG1 protein expression in human colorectal cancer cells." (PMID 29649138, 2018). "In the present study, we demonstrated that FoxM1 and PTTG1 were concordantly up-regulated in colorectal cancers." (PMID 26264222, 2015). "Analyses of multiple microarray datasets derived from human colorectal cancer indicated that correlation levels of FoxM1 and pituitary tumor transforming gene (PTTG1) are highly concordant (R = 0.68 ~ 0.89, p = 2.1E-226 ~ 9.6E-86)." (PMID 26264222, 2015). "EMSA and ChIP assays confirmed that FoxM1 directly binds to PTTG1 promoter at the −391 to −385 bp region in colorectal cancer cells." (PMID 26264222, 2015). "FoxM1 binds to PTTG1 promoter to promote PTTG1 transcription, and FoxM1-PTTG1 pathway promotes colorectal cancer migration and invasion." (PMID 26264222, 2015). "FoxM1 binds to PTTG1 promoter to enhance PTTG1 transcription, and FoxM1-PTTG1 pathway promotes colorectal cancer migration and invasion." (PMID 26264222, 2015). "Bioinformatic analyses indicated that FoxM1 and PTTG1 are concordantly expressed in human colorectal cancer tissues, suggesting PTTG1 is a potential target of FoxM1." (PMID 26264222, 2015). "PTTG1 expression has been correlated with lymph node invasion in colorectal cancer and was proposed as an independent prognostic molecular biomarker." (PMID 18426563, 2008). "Overexpressing PTTG1 was correlated with worse prognosis in tumors, such as ovarian cancer, cervical cancer, renal cell carcinoma, and colorectal cancer." (PMID 40407808, 2025). "In addition, PTTG1 was upregulated by FOXM1 in colorectal cancer, suggesting its role in migration and invasion of cancer cells." (PMID 33173433, 2020). "Higher levels of PTTG1 expression may enhance the apoptotic effects of the anti-microtubule drug BPR0L075 on human colorectal cancer cells." (PMID 29649138, 2018). "FoxM1 activates PTTG1 and promotes migration and invasion of colorectal cancer cells." (PMID 26264222, 2015). "PTTG1 is required for FoxM1 to promote colorectal cancer cell migration and invasion." (PMID 26264222, 2015). "To determine whether FoxM1 modulates PTTG1 expression in colorectal cancer cells, we first examined FoxM1 expression in 61 colorectal cancer cell lines using microarray data derived from CCLE (Cancer Cell Line Encyclopedia)." (PMID 26264222, 2015). "Boyden chamber assay indicated that FoxM1 and PTTG1 siRNAs attenuated migration and invasion of HCT116 and SW620 colorectal cancer cells." (PMID 26264222, 2015). "Boyden chamber assay indicated that both FoxM1 and PTTG1 regulate migration and invasion of HCT116 and SW620 colorectal cancer cells." (PMID 26264222, 2015). "PTTG1 over-expression has been correlated to a worse prognosis in thyroid, lung, colorectal cancer patients, and it can not be excluded that this effect may also occur in other tumor types." (PMID 18426563, 2008).
ovarian carcinoma (18 papers, 2008 to 2025). A malignant neoplasm originating from the surface ovarian epithelium. "PTTG1 is a therapeutic target in ovarian cancer and is associated with functions including DNA repair, angiogenesis, and cell development." (PMID 29321820, 2017). "Similarly, PTTG1 has been previously implicated in regulation of cancer stemness in ovarian cancer." (PMID 37533202, 2023). "In ovarian cancer, inhibition of PTTG1 suppressed cell proliferation and tumor growth in nude mice model." (PMID 40076450, 2025). "HGF, c-MET and PTTG1 are potential therapeutic targets for inhibiting the abdomen–pelvic/peritoneal spread of endometriosis and ovarian cancer." (PMID 40076450, 2025). "Shah and Kakar demonstrated that PTTG1 is able to induce the EMT process by regulation of multiple key players in ovarian cancer cell lines." (PMID 36230799, 2022). "Suppression of PTTG1 by small interfering (si)RNA knockdown resulted in decline transforming ability of both H1299 cells and A2780 ovarian carcinoma cells as well as attenuated tumor growth." (PMID 33173433, 2020). "Many of the genes from this set that are highly expressed in CEPI promote entry into and progression through the cell cycle (e.g., FOXM1, PTTG1, AURKA) and have been previously associated with stage III epithelial ovarian cancers." (PMID 20040092, 2009). "We also observed the overexpression of PTTG1 in tissues of ovarian cancer from different patients (Figure." (PMID 19014669, 2008). "Furthermore, PTTG1 was consistently upregulated in the migrated cells in both endometriosis and ovarian cancer." (PMID 40076450, 2025). "PTTG1 is expressed in migrated cell populations in both endometriosis and ovarian cancer." (PMID 40076450, 2025). "Another study suggests PTTG1 expression levels may be a biomarker for prediction of sensitivity to saracatinib in all types of ovarian cancer." (PMID 37087441, 2023). "PTTG1 triggered EMT by decreasing E-cadherin expression in human ovarian cancer cells." (PMID 27893422, 2017). "Given that PTTG1 is expressed in the migration population of EMS, similar to ovarian cancer, inhibition of PTTG1 may delay the progression of endometriosis and ovarian cancer." (PMID 40076450, 2025). "Another study demonstrated that PTTG1 promotes M2 macrophage polarization through the cGMP/PKG signaling pathway and facilitates epithelial-mesenchymal transition (EMT) progression in human epithelial ovarian cancer cells." (PMID 41001045, 2025).
prostate carcinoma (14 papers, 2015 to 2025). A carcinoma that arises from epithelial cells of the prostate gland. "Elevated expressions of PTTG1 and Ki-67 are linked to higher tumor grade, greater proliferative activity, and poorer clinical outcomes in meningiomas and prostate cancer." (PMID 41573212, 2025). "E2F4 is known to repress Bub3 and Pttg1, two important mitotic genes, in prostate cancer and play a crucial role in G2 arrest." (PMID 38173042, 2024). "The present study is the largest published study on the prognostic value of BUB3, CCNB1, and PTTG1 expression in prostate cancer." (PMID 31801961, 2020). "The low expression of CCNB1 and PTTG1 observed in this study is in agreement with the low proliferation rates in prostate cancer and comparable to the protein levels found in small-scale studies in prostate cancer." (PMID 31801961, 2020). "Upregulation of PTTG1 was shown in a study describing a gene-expression signature connected to metastasis in solid tumors, including prostate cancer, and underscores the potential usefulness of this gene in prostate cancer prognostication." (PMID 31801961, 2020). "PTTG1 overexpression induced an increase in mitotic cells and apoptosis in paclitaxel-treated prostate cancer cell lines." (PMID 29649138, 2018). "As better risk stratification of patients with prostate cancer is needed, we aimed to investigate whether the expression of BUB3, CCNB1 and PTTG1 could independently predict recurrence after radical prostatectomy." (PMID 31801961, 2020). "The mitotic checkpoint protein BUB3, cyclin B1 (CCNB1) and pituitary tumor-transforming 1 (PTTG1) regulates cell division, and are sparsely studied in prostate cancer." (PMID 31801961, 2020). "Scoring of PTTG1 and CCNB1 may prove challenging due to the low abundance of these proteins in prostate cancer." (PMID 31801961, 2020).
liver cancer (12 papers, 2018 to 2025). An epithelial or non-epithelial malignant neoplasm that arises from the liver. "PTTG1 was predominantly expressed in both the cytoplasm and nuclei of liver cancer cells, with minor expression observed in the cytoplasm of adjacent tissues." (PMID 40315269, 2025). "The mRNA expression of 4 hub genes, includingCDK1, HMMR, PTTG1, and TTK, were significantly associated with the survival probability of liver cancer patients in TCGA." (PMID 34187556, 2021). "PTTG1 translocation led to liver cancer cell proliferation, invasion, and tumor growth." (PMID 35805898, 2022). "The mechanism of PTTG1 in liver cancer is worthy of an in-depth study." (PMID 34187556, 2021). "We hypothesized that PTTG1 was closely related to the immune response, and the mechanism of PTTG1 in liver cancer is needed to be further explored." (PMID 34187556, 2021). "Moreover, some scholars have claimed that aconitum coreanum polysaccharide fraction (CACP) abates the growth of liver cancer cell H22 in vitro and in vivo by inhibiting PTTG1." (PMID 34025420, 2021). "Huang, found that long chain noncoding RNA PTTG3P by raising PTTG1 and activating PI3K/AKT signaling pathway to promote cell growth and metastasis of liver cancer." (PMID 35033076, 2022). "The immunohistochemistry results confirmed that the protein expression levels of CDK1, HMMR, PTTG1, and TTK were higher in liver cancer tissues than normal liver tissues." (PMID 34187556, 2021). "The correlation between the mRNA expression of CDK1, HMMR, PTTG1, TTK, and infiltrating immune cells in liver cancer was analyzed by using the TIMER database." (PMID 34187556, 2021). "The correlation between CDK1, HMMR, PTTG1, and TTK and gene markers for different subsets of immune cells in liver cancer were analyzed through the TIMER-related modules." (PMID 34187556, 2021). "Based on the protein expression data from the HPA, the protein expression levels of CDK1, HMMR, PTTG1, and TTK in liver cancer tissues and normal liver tissues were compared by utilizing the antibodiesCAB003799, CAB002433, HPA008890, and CAB013229." (PMID 34187556, 2021). "Four of these hub genes, including CDK1, HMMR, PTTG1, and TTK, were filtered out as potential biomarkers for diagnosis and prognosis of liver cancer." (PMID 34187556, 2021). "Furthermore, the relationship between SCNA of the CDK1, HMMR, PTTG1, and TTK and infiltrating immune cells in liver cancer was explored via using TIMER." (PMID 34187556, 2021). "The CDK1, HMMR, PTTG1, and TTK were hub genes in liver cancer; hence, they might be potential biomarkers for diagnosis, prognosis, and targeted therapy of liver cancer." (PMID 34187556, 2021). "The results showed that UBE2C, PTTG1, TOP2A and SPP1 were positive, FCN3, SLC22A1, ADH4, CYP2C8, SLC10A1, and FBP1 were negative in liver cancer tissues." (PMID 38664521, 2024). "The mRNA levels and protein levels of CDK1, HMMR, PTTG1, and TTK were higher in liver cancer tissues compared to normal tissues, which showed excellent diagnostic and prognostic value." (PMID 34187556, 2021).
thyroid cancer (12 papers, 2008 to 2024). "PTTG1, which is targeted by miR-146a and miR-146b, is also regulates thyroid cancer." (PMID 28427206, 2017). "Interestingly, on the same chromosome, almost 50 kb separate the pre-miR-146a from the pituitary tumor-transforming gene 1 (PTTG1), a proto-oncogene involved in several tumors, including thyroid cancers." (PMID 24145614, 2013). "Moreover, several studies have shown the involvement of PTTG1 in the onset and/or progression of different types of tumors, including thyroid cancers." (PMID 24145614, 2013). "Here, we first investigate whether epigenetic and structural alterations may explain PTTG1 upregulation in both tumor cell lines and thyroid cancer biopsies." (PMID 18426563, 2008). "We also tested whether the CpG island mapping PTTG1 proximal promoter evidenced a differential methylation pattern in differentiated thyroid cancer biopsies concordant to their PTTG1 immunohistochemistry status." (PMID 18426563, 2008). "Finally, we have recently reported that PTTG1 is highly expressed in two thirds (65%) of the differentiated thyroid cancers of Spanish origin, and was shown to be an independent prognostic factor for persistent disease among DTC patients." (PMID 18426563, 2008). "However, it could be found that the PTTG1 expression was lower in Thyroid carcinoma (THCA) than the normal tissue (p < 0.001)." (PMID 35281830, 2022). "Pituitary tumor transforming gene 1 (PTTG1) and PTTG-1 binding factor (PBF) overexpression in thyroid cancers can decrease the NIS protein levels, possibly by repressing NIS mRNA transcription or by removing the protein from the PM." (PMID 34771624, 2021). "The PTTG1 and PBF expressions were upregulated in thyroid cancer and were reported to stimulate bFGF expression." (PMID 19014669, 2008). "Interestingly, on the same chromosome 5, ∼50 kb separate pre-miR-146a (OMIM*610566) from the pituitary tumor-transforming gene 1 (PTTG1) (OMIM*604147), reported to be overexpressed in thyroid carcinomas." (PMID 24145614, 2013). "They took among the various cell lines studied, one human anaplastic thyroid cancer and one K18 thyroid cancer cell line, and treated them with CDODA-Me and CF3DODA-Me, observing a reduction in both gene and protein expression of pituitary tumor-transforming gene-1 (PTTG-1)." (PMID 39409128, 2024).
cervical carcinoma (11 papers, 2006 to 2025). A carcinoma arising from either the exocervical squamous epithelium or the endocervical glandular epithelium. "A crosstalk has been reported between ZEB1 and PTTG1, involving miR-3666 in cervical cancer cell lines." (PMID 36230799, 2022). "In terms of biological function, PTTG1 is regulated by various lncRNAs and miRNAs and plays a role in the malignant progression of cervical cancer." (PMID 34530829, 2021). "PTTG3P, a pseudogene of PTTG1 which is upregulated in many types of cancer, was found to promote cervical cancer growth and metastasis by enhancing PTTG1 expression." (PMID 32185172, 2020). "Transfection of antisense PTTG1 mRNA downregulated its expression, and decreased the growth of cells of the human cervical cancer HELA-S3 cell line and increased apoptosis." (PMID 33173433, 2020). "In cervix carcinoma cells inhibition of PTTG-1 using antisense-ODNs leads to growth inhibition and increased apoptosis." (PMID 16426442, 2006). "Another study constructed a six-gene prognostic model, including PTTG1, that could become the new promising target for the cervical cancer treatment." (PMID 37768206, 2023).
colon carcinoma (11 papers, 2011 to 2024). "PTTG1 loss was also demonstrated to increase colon cancer cell sensitivity to ionizing radiation, adriamycin, doxorubicin or Trichostatin A." (PMID 29371923, 2017). "As FoxM1, abnormal transcription and expression of PTTG1 is involved in colon cancer progression and metastasis and is a FoxM1 targeted gene." (PMID 30744076, 2019). "Pituitary tumor-transforming gene-1 (PTTG1) is overexpressed in different cancers including colon cancer." (PMID 30744076, 2019). "The in vivo tumor xenografts also provided evidence that PTTG1 participates in the FoxM1-mediated liver metastases of colon cancer." (PMID 26264222, 2015). "In present study, we identified PTTG1 as a FoxM1 target gene in colon cancer, which provides a mechanism of FoxM1 involved in the metastasis of malignances." (PMID 26264222, 2015). "SW620 colon cancer cells transfected with empty vector or PTTG1 plasmids or PTTG1 siRNA were treated with doxorubicin." (PMID 21858218, 2011). "PTTG1 in moreover an oncogene since its overexpression induces aneuploidy and stimulates tumor formation, as previously reported in pituitary, thyroid, breast, uterine, ovarian, lung and colon tumors." (PMID 31572301, 2019). "PTTG1 also regulated SW620 colon cancer cells response to doxorubicin and TSA mediated by p21." (PMID 21858218, 2011). "This study revealed that remimazolam promoted the cell-cycle progression and proliferation of HCT8 colon cancer cells by upregulating CDK1, PTTG1, CDC25C, CDK4, PLK1, PCNA, Ki67, RNASEH2B, FEN1, Cyclin D1,CD44 CDK2, CDKN3, CDC45, IQGAP3, and CDK6." (PMID 38725628, 2024). "To obtain insight into the role of PTTG1 in colon cancer cells, we performed ingenuity pathway analysis (IPA) using the differentially expressed genes present in PTTG1−/− HCT116 cell." (PMID 26264222, 2015). "To investigate the role of PTTG1 and FoxM1 in colon cancer metastasis, we stably expressed FoxM1 in PTTG1+/+ and PTTG1−/− HCT116 cells, and implanted these cells into the spleen of nude mice to induce liver metastases." (PMID 26264222, 2015). "Moreover, knockdown of Sp1, Sp3 and Sp4 (in combination) in RKO colon cancer cells also decreased expression of EGFR, cyclin D1, p65 and PTTG-1, confirming the role of Sp transcription factors in regulating expression of these genes." (PMID 21864401, 2011). "Moreover combined knockdown of Sp1, Sp3 and Sp4 using an oligonucleotide cocktail (iSp) also decreased expression of p65, PTTG-1, EGFR and cyclin D1 in RKO cells confirming their regulation by Sp transcription factors in colon cancer cells." (PMID 21864401, 2011).